SNORA78 (small nucleolar RNA, H/ACA box 78)
Synonyms: ACA64
Gene: Small nucleolar RNA gene on chromosome 16 (1,965,184 to 1,965,310, forward strand). Ensembl gene ENSG00000273587.
Gene Ontology:
Biological process: RNA processing
Cellular component: nucleolus
Homologues: Orthologues: chimpanzee SNORA78 (99% identical), mouse Snora78 (85% identical), rat LOC120095472 (83% identical).
Diseases named in the same sentence as SNORA78 in open-access papers:
SNORA78 is named in the same sentence as 1 disease in open-access papers, as found by Europe PMC text mining. Sharing a sentence is not in itself a finding about the gene and the disease.
SNORA78 shares sentences with these, for which no sentence is quoted: tumor (1 paper).